TGOLN2 (trans-golgi network protein 2)
Description:
May be involved in regulating membrane traffic to and from trans-Golgi network.
Synonyms: hTGN46; hTGN48; hTGN51; TGN46; TGN51; TGN48; TGN38; TTGN2
Tractability: Antibody: its Gene Ontology location is reachable by antibodies, with high confidence; UniProt places it where antibodies can reach, with medium confidence; UniProt predicts a signal peptide or a membrane-spanning region. PROTAC: ubiquitination databases record sites on it; its protein half-life has been measured.
Gene: Protein-coding gene on chromosome 2 (85,318,027 to 85,328,251, reverse strand). Ensembl gene ENSG00000152291.
Subcellular location: Cell membrane; Golgi apparatus, trans-Golgi network membrane
Subcellular location (Human Protein Atlas): Golgi apparatus; Nucleoplasm
Pathways (Reactome):
Vesicle-mediated transport: Cargo recognition for clathrin-mediated endocytosis; Clathrin-mediated endocytosis; Golgi Associated Vesicle Biogenesis; Retrograde transport at the Trans-Golgi-Network
Metabolism of proteins: Post-translational protein phosphorylation; Regulation of Insulin-like Growth Factor (IGF) transport and uptake by Insulin-like Growth Factor Binding Proteins (IGFBPs)
Gene Ontology:
Molecular function: protein binding
Cellular component: Golgi apparatus; trans-Golgi network; clathrin-coated endocytic vesicle membrane; endoplasmic reticulum lumen; endosome; plasma membrane; trans-Golgi network transport vesicle; transport vesicle
Genetic constraint (gnomAD): Loss-of-function variants: 19 observed, 30.52 expected, observed/expected ratio (o/e) 0.62, 90% interval 0.43 to 0.91. The upper end of that interval is the gene's LOEUF score, 0.91, which puts it in group 3 of 6, group 1 being the genes least tolerant of losing a copy. Missense variants: 540 observed, 576.46 expected, observed/expected ratio (o/e) 0.94, 90% interval 0.87 to 1.01. Synonymous variants: 222 observed, 236.05 expected, observed/expected ratio (o/e) 0.94, 90% interval 0.84 to 1.05.
Homologues: Orthologues: chimpanzee TGOLN2 (97% identical), macaque TGOLN2 (81% identical), dog TGOLN2 (38% identical), rat Tgoln2 (36% identical), mouse Tgoln1 (35% identical), tropical clawed frog tgoln2 (20% identical), zebrafish tgoln2 (16% identical).
Diseases named in the same sentence as TGOLN2 in open-access papers:
TGOLN2 is named in the same sentence as 17 diseases in open-access papers, as found by Europe PMC text mining. Sharing a sentence is not in itself a finding about the gene and the disease. The quoted sentences say what the papers report.
Multiple Myeloma (1 paper, 2024). "By validating CancerHubs predictions we demonstrated that TGOLN2 is a protein with tumour suppressor features in Multiple Myeloma, Breast and Prostate Cancer and that EFTUD2 has an oncogene-like behaviour in Multiple Myeloma." (PMID 39657701, 2024). "Through this approach, we identified TGOLN2 as a putative novel broad cancer tumour suppressor and EFTUD2 as a putative novel multiple myeloma oncogene." (PMID 39657701, 2024). "By exploring the data produced, we discovered several putative novel broad cancer and cancer-specific genes and validated two of them: TGOLN2, a putative novel broad cancer tumour suppressor and EFTUD2, a new putative oncogene in Multiple Myeloma." (PMID 39657701, 2024).
cancer (3 papers, 2011 to 2024). A tumor composed of atypical neoplastic, often pleomorphic cells that invade other tissues. "At first, to formally demonstrate that TGOLN2 had tumour suppressor properties, we selected cell lines with high TGOLN2 levels deriving from tumours for which TGOLN2 was predicted to be a cancer hub." (PMID 39657701, 2024). "Overall these results indicate not only that our approach efficiently defines already established cancer-related genes, but, more importantly, that it can predict novel cancer hubs, e.g. TGOLN2, HNRNPL, and NHRNPU." (PMID 39657701, 2024). "Starting from the seed lists, we selected one broad cancer tumour suppressor-like gene and one cancer-specific gene with oncogenic potential to validate, namely TGOLN2 and EFTUD2." (PMID 39657701, 2024). "Overall, these results validate the efficacy of CancerHubs predictions and establish TGOLN2 as a novel broad cancer hub with tumour suppressor-like properties and EFTUD2 as a novel MM hub with oncogenic properties." (PMID 39657701, 2024). "Three genes, PPP1CA, PAAF1, and TGOLN2 were significantly upregulated in cancer tissues (P=0.0154, P=0.0298, and P=0.0312 respectively)." (PMID 21847129, 2011). "Interestingly, the expression patterns of DCAF4, COX10, and TGOLN2 presented the best tool set to identify and separate cell lines with their respective irinotecan-resistant variants from other pairs of parental–resistant CRC cells lines that were delivered from different cancer locations or stages." (PMID 35885025, 2022). "Here, we validated two selected cancer-related genes from the seed lists: TGOLN2, a new broad cancer hub with tumour suppressor-like properties and EFTUD2, a novel MM-specific hub with oncogenic potential." (PMID 39657701, 2024). "Besides TGOLN2 and EFTUD2, our method predicted several other broad cancer or cancer-specific hubs." (PMID 39657701, 2024).
tumor (3 papers, 2015 to 2024). "We found not only that TGOLN2 donwmodulation favoured an increase in cell metabolism, but also that such increase was again proportional with TGOLN2 downmodulation, strenghtening the idea that TGOLN2 could actually function as a tumour suppressor." (PMID 39657701, 2024). "Overall, we showed that TGOLN2 has tumour suppressor-like properties in BC, MM and PrC." (PMID 39657701, 2024).
TGOLN2 also shares sentences with these, for which no sentence is quoted: infection (14 papers); viral infection (3); colon cancer (2); Cerebral ischemia (1); cystinosis (1); HCMV infection (1); hepatitis B virus infection (1); hepatoma (1); leukemia (1); lung adenocarcinoma (1); melanoma (1); pancreatic adenocarcinoma (1); prostate carcinoma (1); small cell lung carcinoma (1).